VGLL1 (vestigial like family member 1)
Diseases named in the same sentence as VGLL1 in open-access papers (continued):
Sharing a sentence is not in itself a finding about the gene and the disease.
cancer (continued). "This study aimed to identify common and unique VGLL1-dependent functions in tumor cells derived from 3 different cancer types that may contribute to disease progression." (PMID 38912065, 2024). "The ASXL2 gene, also shown to be upregulated by VGLL1, is reported to regulate EMT transition during trophoblast differentiation and has been linked to the promotion of tumorigenesis and cell proliferation in a variety of cancer types." (PMID 38912065, 2024). "We therefore set out to determine whether cell lines derived from these cancer types could be targets for VGLL1-specific CTLs." (PMID 33087697, 2020). "Gene expression profiling reveals VGLL1 as a member of a unique group of cancer-placenta antigens (CPA) that may constitute immunotherapeutic targets for patients with multiple cancer types." (PMID 33087697, 2020). "Importantly, shVGLL1-expressing NUGC3 cells suppressed lung metastasis in a mouse model, implying a crucial role of VGLL1 in cancer metastasis." (PMID 31816819, 2019). "We then investigated the role of VGLL1 in cancer metastasis." (PMID 31816819, 2019). "Therefore, in the current study we investigated the effect of VGLL1 on cell proliferation and invasion by downregulation or upregulation of its expression levels in cancer cells originating from pancreas, breast, and placenta using siRNA knockdown or retrovirus overexpression systems." (PMID 38912065, 2024). "However, the molecular mechanism of VGLL1 in cancer is still poorly characterized." (PMID 31816819, 2019). "On the other hand, VGLL1 and VGLL3 have been shown to promote cancer cell proliferation through interactions with TEAD." (PMID 41347094, 2025). "Although many questions remain regarding the precise roles VGLL1 plays in promoting gene transcription, emerging evidence supports that effective targeting of this co-transcriptional activator may greatly benefit many patients suffering from different types of cancer." (PMID 38912065, 2024). "Collectively, our results show that VGLL1 is an immunogenic TAA target with strong potential for enabling CTL-mediated therapies for PDAC and multiple other cancer types." (PMID 33087697, 2020). "Here, the authors identified a peptide derived from Vestigial-like 1 (VGLL1) as a shared, potentially therapeutic CTL target expressed by multiple cancer types." (PMID 33087697, 2020). "Collectively, our study shows that VGLL1 is a promising TAA target that can be used in immune-based therapies to address a serious unmet need in patients with PDAC and multiple other cancer types." (PMID 33087697, 2020). "The structural similarities between VGLL1 and YAP or TAZ suggest the formation of VGLL1–TEAD complex for cancer malignancy." (PMID 31816819, 2019). "However, the molecular function of VGLL1 in cancer remains unclear." (PMID 31816819, 2019). "Intriguingly, we found that none of the major cancer cell subclusters (Ep_TRIM54, Ep_VGLL1, and Ep_KRT6A) exhibited preferences for Fb_LRRC15." (PMID 38297291, 2024). "Vestigial-like 1 (VGLL1) is a mammalian co-transcriptional activator that has been shown to play an important role in placental development and is also highly expressed in various cancer types." (PMID 38912065, 2024). "Furthermore, previous studies have shown that VGLL1 can directly interact with TEAD1 and TEAD4 in cancer cells." (PMID 38912065, 2024). "The impact of VGLL1 in cancer has not been fully elucidated and no VGLL1-targeted therapy currently exists." (PMID 38912065, 2024). "Expanded VGLL1-specific CTLs not only recognized and killed a panel of allogenic PDAC tumor lines, but also demonstrated reactivity against A*0101-expressing tumor cells derived from five other cancer types." (PMID 33087697, 2020). "Collectively, this data suggested that VGLL1 may constitute a safe, targetable TAA for multiple cancer types." (PMID 33087697, 2020).
cancer (continued). "Comparative gene expression profiling revealed that VGLL1 is a member of a unique group of cancer-placenta antigens (CPA) that demonstrate high expression in placenta, low to absent expression in essential normal tissues, and overexpression in several different cancers." (PMID 33087697, 2020). "Interestingly, many of the genes regulated by VGLL1 have not yet been mapped to a specific pathway but may play a substantial role in driving cancer progression." (PMID 38912065, 2024).
tumor (8 papers, 2015 to 2026). "In addition, we performed RNA sequencing analysis of these tumor cells to evaluate transcriptional changes associated with regulating VGLL1 protein expression." (PMID 38912065, 2024). "Identification of PTMs that control association of VGLL1-3 with TEADs and development of methods that could specifically repress this complex formation is required for tumor treatment." (PMID 32793503, 2020). "TheEWSR1::VGLL1 fusion was first described in malignantmyoepithelial tumor, a neoplasm of soft tissue." (PMID 41522855, 2026). "By contrast, ectopic overexpression of VGLL1 in PANC1 cells clearly increased the rate of tumor cell proliferation, with a greater than 2-fold increase in cell number by day 7 of culture compared to empty vector-transduced cells." (PMID 38912065, 2024). "Each dot represented a single database entry for the indicated specific TF, with results distinguished by TFs found to bind VGLL1 in multiple tumor cell lines (black), or in individual cell lines: PANC10.05 (red), BT20 (green) and Bewo (blue)." (PMID 38912065, 2024). "This was reminiscent of the reduced proliferation and cell death we observed in tumor cells following VGLL1 knockdown." (PMID 38912065, 2024). "In this study, we showed that VGLL1 is highly expressed in a choriocarcinoma cell line and that VGLL1 expression drove enhanced cell proliferation and invasion in these tumor cells." (PMID 38912065, 2024). "Taken together, our findings provide additional mechanistic evidence that VGLL1 plays an important role in modulating the expression of specific genes involved in driving tumor progression." (PMID 38912065, 2024). "We showed in all 3 tumor cell lines that downregulation of VGLL1 expression inhibited cell proliferation and invasion capacity." (PMID 38912065, 2024). "In normal tissues, VGLL1 is most highly expressed within placental trophoblast cells, which share the common attributes of rapid cellular proliferation and invasion with tumor cells." (PMID 38912065, 2024). "This analysis revealed several gene clusters that were either upregulated or downregulated by VGLL1 in a global or tumor cell-specific fashion." (PMID 38912065, 2024). "Because VGLL1-3 are suggested to be involved in tumor progression, its inactivation is required for tumor treatment." (PMID 32793503, 2020). "Collectively, these results provide evidence that the LSELETPGKY peptide constitutes a shared PDAC tumor antigen that can be effectively targeted with VGLL1-specific CTLs." (PMID 33087697, 2020). "It is worth noting that VGLL1 transcript expression was found to be considerably higher in PDAC tumor cell lines and PDX tissues compared with surgically resected PDAC tumors, likely due to the high stromal content of many PDAC tumors in situ." (PMID 33087697, 2020). "In vivo tumor formation of NUGC3 cells expressing VGLL1-specific shRNAs was significantly reduced when compared to the control." (PMID 31816819, 2019). "Furthermore, our study demonstrated the dependency of tumor cells on VGLL1 expression by showing that downregulation of VGLL1 diminished cell invasiveness, proliferation, and survival." (PMID 38912065, 2024). "Emerging evidence has suggested that tumor cells may co-opt attributes of normal placental VGLL1 function to promote invasion, proliferation, and tumor progression." (PMID 38912065, 2024). "However, its negative impact on survival is most striking in PDAC, suggesting that VGLL1 may play a role in driving tumor aggressiveness." (PMID 33087697, 2020). "This comparison showed a very high degree of overlap in the percentage of target loci where VGLL1 bound compared to those targets previously identified for TEAD1, TEAD2, TEAD3, and TEAD4 (p < 10e-370 for all 3 tumor cell lines)." (PMID 38912065, 2024).
tumor (continued). "Employing an unbiased immunopeptidome analysis of tumor specimens derived from 35 PDAC patients, VGLL1 was identified as a putative shared TAA, ranked second only to MUC16 in terms of tumor expression in comparison to essential normal tissues." (PMID 33087697, 2020). "The high degree of overlap observed for the 4 TEADs in all 3 tumor cell lines suggest that VGLL1 interacts with these TEADs globally and not in a tissue-specific manner." (PMID 38912065, 2024). "This identified a shared HLA-A*0101 restricted peptide derived from co-transcriptional activator Vestigial-like 1 (VGLL1) as a putative TAA demonstrating overexpression in multiple tumor types and low or absent expression in essential normal tissues." (PMID 33087697, 2020). "Interferon-gamma treatment of tumor cell lines did not significantly alter recognition and killing by VGLL1 CTLs." (PMID 33087697, 2020). "To determine if VGLL1 CTLs derived from patient MP015 could recognize allogeneic PDAC tumors, we tested a panel of HLA-A*0101-expressing PDAC tumor cell lines as targets for killing using a 51Cr release assay." (PMID 33087697, 2020).
adenocarcinoma (1 paper, 2019). A common cancer characterized by the presence of malignant glandular cells. "In adenocarcinoma tissues, VGLL1 expression was 55% higher when compared to healthy tissues." (PMID 31816819, 2019).
VGLL1 also shares sentences with these, for which no sentence is quoted: cervical cancer (2 papers); Ewing sarcoma (1); head and neck cancer (1); nasopharyngeal carcinoma (1); neuroblastoma (1); preeclampsia (1); prostate carcinoma (1); schizophrenia (1); schwannoma (1); schwannomatosis (1).